G6PD (glucose-6-phosphate dehydrogenase)
Diseases named in the same sentence as G6PD in open-access papers (continued):
Sharing a sentence is not in itself a finding about the gene and the disease.
malaria (continued). "The cell-free haemoglobin was lower on enrolment compared to G6PD normal uncomplicated malaria patients and exhibited a bimodal pattern with a peak of 6.0 μM 42 h after G6PD normal patients." (PMID 28356147, 2017). "The inclusion of primaquine into national treatment guidelines and its implementation will be essential to the successful elimination of malaria, G6PD testing is currently available in a number of formats." (PMID 28797255, 2017). "Cell-free haemoglobin on enrolment was below the 75% percentile compared to G6PD normal severe malaria patients but increased to 6.7 μM at 72 h." (PMID 28356147, 2017). "In a pilot project in Thailand CareStartTM G6PD RDTs were deployed in 62 selected malaria clinics in 16 provinces (personal communication Suravadee Kitchakam)." (PMID 28381261, 2017). "A number of respondents stated that routine testing would be useful in the context of malaria elimination.“For test[ing] G6PD[activity this] is very useful." (PMID 28797255, 2017). "As G6PDd also affects the clinical presentations of other infections, the benefits of G6PD testing and proper record keeping transcend those of malaria case management." (PMID 29082022, 2017). "Currently only 7 malaria-endemic countries in the Asia–Pacific region and Sri Lanka, which is malaria free, recommend G6PD testing prior to PQ treatment." (PMID 28381261, 2017). "In the absence of prior anti-malarial treatment, his parasitaemia was above the 75% percentile of G6PD normal uncomplicated malaria patients, which was accompanied by an elevated PfHRP2 concentration." (PMID 28356147, 2017). "There is limited information for G6PD-malaria interaction in Pakistan raising several research questions: What is the prevalence of G6PDd in Southern Pakistan?" (PMID 29065882, 2017). "In the present study, the associations between the incidence of uncomplicated malaria and HBB, G6PD and NOS2 gene polymorphisms were determined in a 1 year follow up study." (PMID 28793894, 2017). "About 8% of the people who are exposed to malaria have an inherited disorder that impairs G6PD, leaving them vulnerable to develop clinical consequences (haemolytic anaemia)." (PMID 28535765, 2017). "Glucose-6-Phosphate Dehydrogenase (G6PD) enzyme deficiency is known to offer protection against malaria and an increased selection of mutant genes in malaria endemic regions is expected." (PMID 28152025, 2017). "This indicates that primaquine administration for malaria eradication requires mandatory G6PD testing in Pakistan." (PMID 29065882, 2017). "Low dose primaquine offers a significant strategic advantage in most malaria endemic settings where G6PD screening prior to treatment remains impracticable." (PMID 28591198, 2017). "This study showed an allelic frequency of 3.6% for G6PD-Med in subjects infected with malaria in Southern Pakistan and 2.8% in all tested individuals." (PMID 29065882, 2017). "This study compared the gametocytocidal efficacy of three different single doses of PQ combined with dihydroartemisinin-piperaquine (DHAP) on gametocyte carriage in asymptomatic, malaria-infected, G6PD-normal individuals in The Gambia." (PMID 27825738, 2016). "Very few studies have focused on asymptomatic malaria patients or simultaneously carried out genotypic and phenotypic analysis of G6PD on the same individual as such, this study set out to find a possible correlation of G6PD with asymptomatic malaria in Ghana." (PMID 27456336, 2016). "Glucose-6-phosphate dehydrogenase (G6PD) deficiency causes acute haemolytic anaemia triggered by oxidative drugs such as primaquine (PQ), used for Plasmodiumvivax malaria radical cure." (PMID 26753754, 2016). "The main objective of this study was to assess the distribution of G6PD genotypes among African children from three geographically countries presenting with severe malaria and participating in the SMAC clinical trial on different artesunate treatment regimens." (PMID 27388012, 2016).
malaria (continued). "Haemoglobin (Hb) concentrations varied significantly with gender, age, ethnicity, G6PD status, and malaria species." (PMID 27788243, 2016). "G6PD status is essential to safe treatment with PQ, but that diagnosis is rarely available at the health facilities where most malaria patients present." (PMID 27430544, 2016). "This a preliminary study to assess the prevalence of G6PDd in representative malaria endemic areas of Colombia by measuring G6PD phonotype and genotypes." (PMID 27225440, 2016). "CareStart G6PD, a qualitative G6PD rapid diagnostic test (G6PD RDT) intended for use at point-of-care in impoverished rural settings where most malaria patients live, was evaluated." (PMID 26894297, 2016). "PCR detectable parasite carriage but not parasite carriage by microscopy was significantly (p = 0.038) associated with the G6PD normal genotype, which slightly supports previous reports that suggests the G6PD trait offers some protection from malaria." (PMID 27456336, 2016). "About 8% of people exposed to malaria have an inherited disorder that impairs G6PD activity, leaving them vulnerable to harm by an important therapy against malaria, primaquine." (PMID 26894297, 2016). "Resolving that therapeutic dilemma requires assessment of patient G6PD status at the point-of-care in the impoverished rural tropics, where the vast majority of malaria patients live." (PMID 26894297, 2016). "We do, however, note that the failure to identify G6PD in the original malaria GWAS is likely an artifact of poor coverage in this genic region as well as low frequency of the protective alleles in the studied populations." (PMID 27042214, 2016). "One of these studies investigated the use of two different low doses of primaquine, 0.1mg/kg and 0.4mg/kg, administered together with artemether-lumefantrine (AL) in malaria patients with a known G6PD status." (PMID 27010542, 2016). "In comparison to individuals with uncomplicated malaria, this study population was hyperparasitemic according to the criteria of severe malaria provided by WHO with lower parasitaemia in G6PD deficient individuals." (PMID 27388012, 2016). "Concordance among these studies offers assurance of satisfactory diagnostic performance of the G6PD RDT among settings of distinct G6PDd variant composition, malaria endemicity, and teams managing the evaluation." (PMID 26894297, 2016). "Fully understanding the role of G6PD requires further correlation of enzymatic activity with full sequences of G6PD and surrounding loci, set within large severe-malaria case and control studies." (PMID 25671784, 2015). "Primaquine, the only medicine available for radical cure of P. vivax and Plasmodium ovale malaria, can induce dose-dependent acute haemolytic anaemia (AHA) in G6PD deficient patients." (PMID 26242747, 2015). "D'autres facteurs sont associés à la survenue de la FBH notamment une immunité anti-malaria inadéquate, déficit en G6PD et un mauvais usage de la quinine." (PMID 26966497, 2015). "Currently, two RDTs to detect G6PDd in field conditions (BinaxNOW® G6PD and CareStartTM G6PD) have been evaluated in malaria endemic areas." (PMID 25889063, 2015). "Such balancing mechanisms exist at other malaria candidate loci, including the HbAS sickle trait and G6PD." (PMID 25805752, 2015). "For the treatment of P. vivax malaria, the National Malaria Control Programme recommends the use of primaquine for radical treatment if glucose-6-phosphate dehydrogenase (G6PD) test is normal." (PMID 25880759, 2015). "Our study also demonstrates that the much-needed large-scale studies of severe malaria and G6PD enzymatic function across African populations require the identification and analysis of the full repertoire of G6PD genetic markers." (PMID 25671784, 2015). "This uncertainty is due to G6PD and malaria phenotypic complexity and misclassification, and to genetic differences between populations and the limited numbers of genetic markers (usually 2) considered." (PMID 25671784, 2015).
malaria (continued). "Using these factors, four countries (Bangladesh, Cambodia, Malaysia, and the Philippines), across a variety of income, malaria burden and health capacity levels are reviewed here to assess the possibility and need to implement routine G6PD testing." (PMID 26416229, 2015). "These are exciting and over-due new offerings in the G6PD testing product pipeline, but compared to malaria or HIV RDTs, the pipeline remains very thin." (PMID 26416229, 2015). "Overall, the newly identified polymorphisms explain an additional nominal 4.3% of the variation in risk of severe malaria over and above the combined 7.4% for HbAS (6.3%), ABO blood group (0.2%), α-thalassemia (0.3%), and G6PD (0.5%)." (PMID 25805752, 2015). "The ethical implications of primaquine therapy against malaria transmission and G6PD testing have been discussed recently and are beyond the scope of this report." (PMID 26416229, 2015). "Reliable G6PD PoC tests have the potential to play an essential role in future malaria elimination programmes, however require an improved understanding on how to best integrate routine G6PD testing into different health settings." (PMID 26416229, 2015). "Since 2012 a series of workshops have been held by the Asia Pacific Malaria Elimination Network (APMEN) to discuss G6PD testing in the context of vivax malaria treatment in the Asia Pacific." (PMID 26416229, 2015). "Malaria programme managers also expressed an interest in G6PD prevalence maps, to better assess local haemolytic risks in G6PDd populations." (PMID 25971688, 2015). "The trial aims to determine and compare the effect of three different single doses of PQ combined with an ACT, dihydroartemisinin-piperaquine (DHA-PPQ), on gametocyte carriage in asymptomatic, malaria-infected, G6PD-normal individuals." (PMID 25887344, 2015). "Based on data from our case-control study, the risks of severe malaria and within-hospital death among G6PD c.202T heterozygous girls were significantly lower than in G6PD normal children." (PMID 26686045, 2015). "Further, we established that the G6PD gene is under evolutionary pressure with the likely mechanism being selection by malaria." (PMID 25671784, 2015). "Two point-of-care (PoC) test formats for the measurement of G6PD activity are currently available: qualitative tests comparable to malaria RDT as well as biosensors that provide a quantitative reading." (PMID 26416229, 2015). "In Manaus, a city with high levels of transmission of malaria in the Brazilian Amazon, the prevalence of G6PD was 2.5%." (PMID 26357512, 2015). "The difference in the Mean (±SE) of levels of G6PD enzyme activity among participants with positive malaria parasites (95% CI, 13.0 (±1.81)) compared to those with negative malaria parasites (95% CI, 14.4 (±1.0)) was not significant (P = 0.242)." (PMID 25885097, 2015). "Proportions of the three groups with asymptomatic malaria parasitaemia at baseline were similar (10.3% for G6PD normal, 8.7% for G6PD partial defect and 11.4% in G6PD full defect, P = 0.73)." (PMID 26327623, 2015). "Resolving this dilemma requires the availability of point-of-care G6PD diagnostics practical for use in the impoverished rural tropics where the vast majority of malaria patients seek care." (PMID 26652887, 2015). "The prevalence of G6PD deficiency in Ghana is estimated to be about 12% among pregnant women and 20% G6PD prevalence has been recorded among African children with malaria." (PMID 25470251, 2014). "Malaria incidence rates were 0.56 episodes/year for G6PD wild-type, and 0.52 episodes/year for G6PD A - female heterozygote’s (p = 0.5) and there was only 1 homozygous male followed up actively." (PMID 24943486, 2014). "Developing a robust, quantitative point-of-care G6PD test for field use in low-resource areas is a high priority for overall malaria control and elimination." (PMID 25071003, 2014).
malaria (continued). "The primary demand for G6PD tests comes from malaria control programmes in vivax-endemic countries, where prolonged and higher doses of primaquine are required for radical cure." (PMID 23537118, 2013). "G6PD genotyping should be necessary to get more accurate information about genetics data of this defect in malaria in this settings." (PMID 23767699, 2013). "PBSA and DS contributed in mass blood screening and G6PD, HK and AF contributed in mapping malaria database, SZ, RRA, HH contributed in vector assessment." (PMID 23363768, 2013). "Howes and co-workers have identified 1,734 community G6PD surveys globally of which 1,289 (74%) were conducted in malaria-endemic countries and used this evidence-base to model a continuous prevalence map of the deficiency." (PMID 23537118, 2013). "There is a growing awareness that robust and reliable G6PD tests that can be used in remote, malaria-endemic regions are needed." (PMID 23537118, 2013). "Variants in genes residing at these three loci (HBB, HBA1/HBA2, and G6PD) confer resistance to malaria in Africans." (PMID 23696099, 2013). "Variants in genes residing in these loci (i.e., HBB, HBA1/HBA2, and G6PD) confer resistance to malaria." (PMID 23696099, 2013). "These efforts included intensive mapping of both vectors and malaria cases, establishment of a comprehensive database, and most recently, aggressive active case finding coupled with surveys to estimate G6PD prevalence and malaria parasite genotypes." (PMID 23363768, 2013). "Three loci previously associated with resistance to malaria—HBB (11p15.4), HBA1/HBA2 (16p13.3), and G6PD (Xq28)—were associated (P ≤ 1 × 10−6) with RBC traits in the discovery cohort." (PMID 23696099, 2013). "A major bottleneck to the adoption of these drugs is determining the G6PD status of a patient presenting with malaria." (PMID 23961874, 2013). "This wide distribution and dominance of G6PD Mediterranean presents a significant hurdle to the malaria elimination programmes in West Asia, which include Azerbaijan, Georgia, Iran, Iraq, Kyrgyzstan, Saudi Arabia, Tajikistan, Turkey, and Uzbekistan." (PMID 24228846, 2013). "The availability of G6PD tests is a critical bottleneck to broader access to drugs that confer radical cure of Plasmodium vivax, a requirement for elimination of malaria." (PMID 23961874, 2013). "Due to these antagonistic selective pressures, G6PD in populations affected by malaria is one of the best examples of balancing selection described in the human genome." (PMID 23071458, 2012). "Haemoglobinuria can also occur in patients with normal erythrocyte G6PD levels who receive quinine for severe malaria." (PMID 23039275, 2012). "The sickle-cell trait (HbS), G6PD, and ABO blood group, are amongst a number of host genes with polymorphisms found to reduce the risk of severe malaria." (PMID 22615793, 2012). "A study in Mali of children with uncomplicated or complicated malaria, reported a G6PD*A- prevalence of 12.9%; about the same as reported here (10.5%)." (PMID 21849081, 2011). "The primary objective of this study was to describe the prevalence of G6PD genotypes in African malaria patients who participated in two CDA Phase III clinical trials." (PMID 21849081, 2011). "G6PD genotype and phenotype were determined for malaria patients enrolled in the chlorproguanil-dapsone-artesunate (CDA) phase III clinical trial programme." (PMID 21849081, 2011). "Of 2264 malaria patients enrolled, 2045 had G6PD genotype available and comprised the primary analysis population (1018 males, 1027 females)." (PMID 21849081, 2011). "This study reports the frequency of G6PD genotypes and phenotypes in malaria patients who participated in two Phase III clinical trials of chlorproguanil-dapsone-artesunate (CDA)." (PMID 21849081, 2011). "Those SNP associations with severe malaria are well known and are commonly reported in the literature: CR1, IL4, TNF, G6PD, IL10." (PMID 20459687, 2010).
malaria (continued). "Vivax malaria, often incorrectly assumed to be benign, seems likely to exert evolutionary pressure for retention of the G6PD trait in human populations." (PMID 20520804, 2010). "A published WST8/1-methoxy PMS method was adapted to assay G6PD activity in a 96-well format using dried blood spots, and used it to undertake population screening within a malaria survey undertaken in Isabel Province, Solomon Islands." (PMID 20684792, 2010). "Statistical analyses indicated that participants with reduced G6PD levels were about one-fifth as likely to develop P. vivax malaria as those with normal G6PD levels after allowing for other factors that might affect their susceptibility to malaria, an adjusted odds ratio (AOR) of 0.18." (PMID 20520804, 2010). "All serious adverse events in the AL group were in G6PD-normal patients, except one case of malaria in a heterozygous female." (PMID 19690618, 2009). "Most studies of IVH in malaria have focussed on the influence of glucose 6-phosphate dehydrogenase (G6PD), and the role played by antimalarial drugs such as chloroquine." (PMID 18086298, 2007). "On the contrary, the district with the highest malaria incidence rate showed the lowest G6PD prevalence rate." (PMID 16780577, 2006). "The discrepancy between the result of this study and the cited work may be because of differences in assay methods, promptness in assaying for G6PD after sample collection, and level of malaria endemicity in the geographical locations." (PMID 41200155, 2025). "The pooled analysis showed that one device, the STANDARD G6PD Test (SD Biosensor, RoK), performed better at measuring G6PD activity compared to the others, although its accuracy may be impacted by the sex and malaria status of the patient." (PMID 40132008, 2025). "Prescriptions for antimalarials should consider G6PD status, especially in malaria-endemic areas." (PMID 40225210, 2025). "For example, high CrF of HBB and G6PD in Africans can be attributed to malaria resistance." (PMID 40162233, 2025). "For example, the missense causal variants of HBB and G6PD for sickle cell disease and anaemia, respectively, were >1,500× more common in AFR versus NFE, owing to their protection against severe malaria and the fact that 95% of malaria cases occur in Africa51." (PMID 40770095, 2025). "This may introduce errors and biases in analyzing G6PD activity among heterozygous females and its impact on malaria resistance." (PMID 40993672, 2025). "Since its inclusion in the Thailand Clinical Practice Guidelines for Malaria Case Management in 2019, the quantitative G6PD test has been routinely used at higher-level health facilities, where healthcare providers have been trained to support P. vivax radical cure with primaquine." (PMID 40274286, 2025). "Secondly, the significant correlation between a high quantile of G6PD cases and a low quantile of malaria cases encourages further investigation of this hypothesis based on the expanded data collection efforts as already underway at the Malaria Atlas Project." (PMID 38179076, 2024). "The frequency of G6PD mutations (50.74%) was higher among 337 malaria-negative samples with 171 samples carrying G6PD genotypes that were predominantly multiple mutations." (PMID 38308253, 2024). "Adoption and fidelity to guidelines are ensured by balancing the need to expand access to radical cure, with malaria elimination as the end goal, and the risk of severe drug-induced hemolysis when primaquine is prescribed without G6PD testing." (PMID 39028699, 2024). "None of the patients with normal G6PD activity during the initial phase (D1–D3) of the malaria episode (n = 44) was categorized as G6PD-deficient at D14." (PMID 38725027, 2024). "They found that G6PD activity was significantly higher during the malaria episode." (PMID 38725027, 2024).